ENSG00000141979 (novel protein)
Gene: Protein-coding gene on chromosome 19 (16,479,067 to 16,628,204, reverse strand). Ensembl gene ENSG00000141979.
Genetic constraint (gnomAD): Missense variants: 553 observed, 575.21 expected, observed/expected ratio (o/e) 0.96, 90% interval 0.9 to 1.03. Synonymous variants: 239 observed, 254.24 expected, observed/expected ratio (o/e) 0.94, 90% interval 0.85 to 1.05.